ZNF542P (zinc finger protein 542, pseudogene)
Description:
May be involved in transcriptional regulation.
Synonyms: DKFZp686B2197; formerly ZNF542
Gene: Transcribed unprocessed pseudogene on chromosome 19 (56,373,250 to 56,377,972, forward strand). Ensembl gene ENSG00000240225.
Subcellular location: Nucleus
Diseases named in the same sentence as ZNF542P in open-access papers:
ZNF542P is named in the same sentence as 1 disease in open-access papers, as found by Europe PMC text mining. Sharing a sentence is not in itself a finding about the gene and the disease. The quoted sentences say what the papers report.
hepatoma (2 papers, 2018 to 2023). "Intracellular cholesterol ester levels upon simvastatin treatment were raised after ZNF542P knocking-down in a human hepatoma cell line." (PMID 37325631, 2023).